RNY1P7 (RNY1 pseudogene 7)
Gene: Miscellaneous RNA gene on chromosome 13 (24,703,556 to 24,703,665, reverse strand). Ensembl gene ENSG00000207474.
Homologues: Orthologues: chimpanzee Y_RNA (100% identical), macaque Y_RNA (94% identical). Paralogues in human: Y_RNA (89% identical), RNY1 (88% identical), Y_RNA (88% identical), Y_RNA (87% identical), Y_RNA (86% identical), Y_RNA (85% identical), RNY1P11 (84% identical), Y_RNA (84% identical), RNY1P8 (83% identical), Y_RNA (83% identical), Y_RNA (82% identical), Y_RNA (81% identical), and 96 more.